KLF14 (KLF transcription factor 14)
Diseases named in the same sentence as KLF14 in open-access papers (continued):
Sharing a sentence is not in itself a finding about the gene and the disease.
cancer (14 papers, 2015 to 2024). A tumor composed of atypical neoplastic, often pleomorphic cells that invade other tissues. "This article summarizes the genetic polymorphisms in KLF14 and the role of the KLF14 gene in transcriptional regulation, age prediction, progression of metabolic disorders, glucose and lipid metabolism, and cancer suppression." (PMID 36837818, 2023). "Several studies have found that elevated KLF14 levels mitigate cancer progression and loss of the KLF14 gene triggers tumorigenesis." (PMID 36837818, 2023). "Normally, KLF14 gene expression is downregulated in cancer, and thus the induced KLF14 expression leads to mitotic arrest." (PMID 36837818, 2023). "KLF14 can be considered as a target for the treatment of cancer as it regulates cell apoptosis, cell proliferation, and differentiation." (PMID 36837818, 2023). "Cell apoptosis, proliferation, and differentiation are regulated by the KLF14 gene, and up-regulation of KLF14 prevents cancer progression." (PMID 36837818, 2023). "KLF14 is present downstream of PKCε and its down regulation in cancer supports cell proliferation and survival." (PMID 35577881, 2022). "Evaluation of gene expression levels for TPD52, miR-124, PKCε and KLF14 with respect to cancer grade was performed." (PMID 35577881, 2022). "In recent years, the number of studies exploring the relationship between KLF14 and cancer has increased." (PMID 35570248, 2022). "KLF14 expression is reduced in many types of human cancer, including breast, lymphatic, cervical, oral cavity, floor of mouth, pancreas and colorectal cancers." (PMID 32705315, 2020). "KLF14, which is often downregulated in human carcinomas, has a function in maintaining the integrity of centrosomes by limiting Plk4 (Polo-like kinase 4) transcription, which is a master regulator of centriole duplication and assembly." (PMID 31406196, 2019). "Oncomine data analysis revealed that multiple human cancers are coincident with increased Plk4 transcription and decreased KLF14 transcription." (PMID 26439168, 2015). "Given there is growing realization that cancer is primarily a metabolic disease, we explored KLF14 transcript levels in human cancers using the Oncomine cancer profiling database." (PMID 26439168, 2015). "As KLF14 inhibition promotes Plk4 transcription, we suggest KLF14 reduction contributes to Plk4 overexpression in human cancers." (PMID 26439168, 2015). "On the other hand, we show that KLF14 overexpression induces mitotic catastrophe, suggesting a possibility for targeting KLF14 for cancer therapy." (PMID 26439168, 2015). "KLF14 mRNA levels were 50% lower in cancer patients as compared to healthy controls (P = 0.0025)." (PMID 35577881, 2022). "Downregulation of KLF14 was observed in metastatic group, suggesting KLF14 down-regulation might have role in cancer metastasis." (PMID 35577881, 2022). "As such, KLF14 presents as a new biomarker or potential target for cancer therapies." (PMID 32548128, 2020). "We therefore further examined the correlation between KLF14 and Plk4 in human cancers." (PMID 26439168, 2015). "Then, KLF14 couples with p300 and CREB-binding protein (CBP) to enhance the transcriptional activation of heme oxygenase 1, which encodes the antioxidant enzyme HO-1 that helps cancer cells restore cellular redox balance under androgen-depleted conditions, resulting in cancer cell survival." (PMID 34405016, 2021). "Moreover, KLF14 is frequently downregulated in human cancers." (PMID 26439168, 2015). "Future clinical investigation of the dysfunction of KLF14 and its connection to centrosome amplification, genomic instability, cancer stage and prognosis may provide more valuable information regarding tumorigenesis and progression, and possibly new therapeutic strategy." (PMID 26439168, 2015). "The present study evaluated differential expression of four genes: PKCε, TPD52, KLF14 and miR-124 that are involved in modulation of Akt/PI3K and Ras/Raf/ERK1/2 signaling in different cancers." (PMID 35577881, 2022).
cancer (continued). "KLF14 and miR-124 mRNA levels were decreased in SOL samples relative to healthy control (p < 0.0001), but to a lesser extent than the reductions in high grade cancer (respectively)." (PMID 35577881, 2022). "Together, these results strongly suggest that there exists a negative correlation between Plk4 and KLF14 expressions in human cancers." (PMID 26439168, 2015).
metabolic disease (10 papers, 2015 to 2024). A congenital disorder (due to inherited enzyme abnormality) or acquired (due to failure of a metabolically important organ) disorder resulting from an abnormal metabolic process. "One of the severe gene irregularities is genetic polymorphism, and a number of studies have been conducted which found that KLF14 SNPs are strongly associated with the development and progression of metabolic disorders." (PMID 36837818, 2023). "There are number of studies that have been conducted on different populations to determine the incidence rate of KLF14 gene polymorphisms and its association with altered lipid levels and the progression of metabolic disorders." (PMID 36837818, 2023). "While the genetic associations of KLF14 variants on metabolic disease have been extensively studied, the role of KLF14 in macrophages is less well characterized." (PMID 29459900, 2018). "The resultant product (transcriptional factor) of KLF14 gene transcription interacts with 10 genes and establishes the protein–protein interactions with 32 proteins, which have a strong association with metabolic disorders and several other biological functions." (PMID 36837818, 2023). "Moreover, KLF14 regulates the efflux of HDL-C and ApoA-1; therefore, alterations in the normal expression of KLF14 triggered by gene polymorphism or epigenetic alteration induce the onset of metabolic disorders." (PMID 36837818, 2023). "Together, these findings indicate that epigenetic regulation–induced KLF14 loss-of-function may trigger the onset of metabolic diseases." (PMID 35456983, 2022). "Taken together, these studies suggest that KLF14 loss-of-function via epigenetic regulation may trigger the onset of metabolic diseases." (PMID 32548128, 2020). "Several KLF14 variants have been identified using genome-wide association studies (GWASs), which lead toward the altered insulin sensitivity, development, and progression of several metabolic diseases, including DM, myocardial infarction, atherosclerotic cardiac diseases, and ischemic stroke." (PMID 36837818, 2023). "GWAS has demonstrated that genomic alterations near the KLF14 gene locus have a significant association with altered HDL-C levels, metabolic disorders, and heart ailments more specifically CADs." (PMID 36837818, 2023). "KLF14 gene expression has been altered during the development and progression of metabolic diseases." (PMID 36837818, 2023). "It has been suggested that the transcription factor KLF14 is involved in metabolic diseases and regulates glucose metabolism through the PI3K/Akt signaling pathways." (PMID 34983946, 2022). "This approach can be optimized to deliver KLF14 agonists to improve adipose tissue function in metabolic disorders." (PMID 32548128, 2020). "In other words, the GWAS signal for metabolic disorders and the expression quantitative trait locus for KLF14 are co-localized." (PMID 32548128, 2020). "Several studies have found that epigenetic alterations in the KLF14 gene may induce metabolic disorders." (PMID 36837818, 2023). "However, the causal variant(s) that is responsible for metabolic disorders, increased T2D/CAD risk, and changes in KLF14 expression remains elusive." (PMID 32548128, 2020).
cardiovascular diseases (6 papers, 2018 to 2023). "An association of the KLF14 rs4731702 SNP and serum lipids as a predictor for cardiovascular disease has also been reported." (PMID 35455702, 2022). "Moreover, recently reported findings revealed that KLF14 exerted a protective role in cardiovascular disease and multiple chronic liver diseases by inhibiting inflammation and fibrosis, which is consistent with our results." (PMID 37551728, 2023). "Similarly, the hypermethylation of KLF14 could have an anti-inflammatory role preventing cardiovascular disease." (PMID 29466246, 2018).
neurological disorders (1 paper, 2022). "Further analysis of other neurological disorder looking at the role KLF14 plays there, could also open the door for the use of HFP animals as a model to study other neurological disorders." (PMID 36061196, 2022).
KLF14 also shares sentences with these, for which no sentence is quoted: endotoxemia (2 papers); Hypercholesterolemia (2); angina (1); autism (1); basal cell carcinoma (1); behavioral disorder (1); colon (1); diabetic nephropathy (1); dyslipidaemia (1); glioblastoma (1); Glomerular sclerosis (1); heart failure (1); Hypertension (1); infection (1); lung adenoma (1); oligodendroglioma (1); psychiatric disorder (1); schizophrenia (1); Silver Russel syndrome (1); thyroid cancer (1).